IL2 (interleukin 2)
Diseases named in the same sentence as IL2 in open-access papers (continued):
Sharing a sentence is not in itself a finding about the gene and the disease.
bladder tumor (5 papers, 2012 to 2023). "So, the first objective of this work was to investigate the mechanism of recognition of bladder tumor cells by IL-2-activated NK cells and the role of several NK receptors mediating degranulation and cytoxicity toward these targets." (PMID 26106390, 2015). "In addition, the importance and role of cytokines, including IL-2, IL-12, IFN-gamma, IL-6, and IL-15, in inhibiting the incidence and growth of bladder tumors has been established." (PMID 22962576, 2012).
brain edema (5 papers, 2016 to 2025). Increased intracellular or extracellular fluid in brain tissue. "The researchers supposed that emotional changes were associated with fluid overload or brain edema caused by increased IL‐2 in the brain." (PMID 32790154, 2020). "The concern with HD IL-2 is the risk of increasing brain edema when administered to patients with untreated CNS metastases, and therefore, most clinicians screen for CNS involvement prior to starting HD IL-2." (PMID 27891227, 2016). "A prominent hypothesis is that IL-2 directly activates IL-2Rαβγc expressing endothelial cells, resulting in the disruption of structural integrity of lung vasculature and the blood-brain barrier (BBB) and leading to pulmonary and brain edema." (PMID 39114660, 2024).
bronchiolitis (5 papers, 2013 to 2025). Inflammation of the bronchioles characterized by swelling of the bronchioles and mucus accumulation. "Several other proinflammatory cytokine pathways were predicted to be affected potential bacterial sRNA modulation, such as IL-1, IL-2, and IL-23, some of which have previously been implicated in bronchiolitis." (PMID 38410509, 2024). "Besides, the Th1-associated cytokines IL-2 and INF-γ and Th1/Th2 cell ratio were markedly reduced in infant serum of acute bronchiolitis." (PMID 34395633, 2021). "Acute bronchiolitis elicited increased levels of IL-4 and IL-10 but decreased level of IFN-γ and IL-2." (PMID 34395633, 2021). "Pathways of several cytokines, such as IL-1, IL-2, and IL-23 were predicted to be significantly upregulated in RSV- compared to RV-only bronchiolitis (z-score = -2.84, p-value = 0.003; z-score = -3.357, p-value = 0.004; and z-score = -2.53, p-value = 0.034, respectively)." (PMID 38410509, 2024).
brucellosis (5 papers, 2008 to 2024). Brucellosis is a bacterial infection that spreads from animals to people via unpasteurized dairy products or by exposure to contaminated animal products or infected animals. "Brucellosis can lower the levels of dehydroepiandrosterone, which is responsible for promoting IL-2 release." (PMID 38794208, 2024). "A fraction of CD8+ T cells show a CD8+ Tmem phenotype of LFA-1hi, CD127hi, KLRG-1lo during the course of chronic brucellosis, while the CD8+ T cell pool as a whole had a very weak polyfunctional cytokine response with diminished co-expression of IFN-γ with TNFα and/or IL-2, a hallmark of exhaustion." (PMID 22558103, 2012). "Thereduction of CD4+/CD25+ T-cells percentage after PHA plus E. coli cultureswas more pronounced in chronic relapsing brucellosis patients (CB1 subgroup),suggesting that relapses in brucellosis might be associated with disturbancesof IL-2/IL-2 receptor system." (PMID 19190764, 2008). "are able to survive and replicate within macrophages, and effective control of brucellosis requires a potent Th1 response to activate cellular mediated immunity which is driven by the production of IFN-γ, IL-2, and TNF-α." (PMID 24040434, 2013). "To further investigate the cytokine production of CD8+ T cells during chronic brucellosis, we examined the expression of IFN-γ, TNF-α, and IL-2 independently of one another." (PMID 22558103, 2012). "Chronic brucellosis patients displaya defective Th1 response to PHA characterized by low-proliferation response ofCD4+ T-lymphocytes, diminished production of IL-2 and IFNγ, and low frequency of CD4+/CD25+ T-cellscompared to acute brucellosis patients." (PMID 19190764, 2008). "IL-2 regulates granzyme expression and is important for the expansion of CD8+ T cells; therefore, minimal IL-2 expression would not favor CD8+ T cells responding to reactivation of senescent brucellosis." (PMID 22558103, 2012).
chorioamnionitis (5 papers, 2020 to 2025). A morphologic finding indicating inflammation of the fetal sac membranes. "Increasing levels of infection-mediated pro-inflammatory cytokines, including TNF, IL-1β, IL-6, and IL-2, have been linked to chorioamnionitis and adverse pregnancy outcomes." (PMID 38877443, 2024). "Elevated levels of pro-inflammatory cytokines such as TNFα, IL-1, IL-12, IL-6, and IL-2 have been linked to chorioamnionitis and therefore elevated levels of these cytokines serve to identify potential pregnancy complications." (PMID 33123496, 2020). "GM-CSF, IL-15, IL-17, IL-2, IL-2R, VEGF, and MIG concentrations were significantly higher in patients with chorioamnionitis than in those without chorioamnionitis." (PMID 41277827, 2025).
chronic fatigue syndrome (5 papers, 2015 to 2024). "Cytokines found elevated in some chronic fatigue syndrome patients include interferon-γ, IL-6, IL-1, IL-2, and TGF-β." (PMID 36510222, 2022).
E. coli infection (5 papers, 2013 to 2024). "In contrast, E. coli infection in normoxia (NE) mildly activates hypoxia, glycolysis, Hedgehog signaling, TNFα signaling via NFκB, IL2 STAT5 signaling, and Notch signaling." (PMID 38720110, 2024). "Interleukin 2 (IL-2) in the E. coli infection group was higher than that in the Gram-positive bacteria infection group (p = 0.023)." (PMID 38066783, 2023). "In differentiating healthy and E. coli infection groups, the AUC values of IL2 were 0.7299, HSPA1B was 0.7931, TNF was 0.8218, and the combination of the three was 0.8793." (PMID 38066783, 2023). "In differentiating E. coli infection from other bacterial infections, the AUC values of IL2 were 0.5846, HSPA1B was 0.7038, TNF was 0.7116, and the combined value of the three was 0.71." (PMID 38066783, 2023). "The levels of the inflammatory factors IL-2, IL-6, TNF-α, and MPO were significantly increased after E. coli infection, while MPX reduced the serum levels of IL-6 (p < 0.01), IL-2, TNF-α, and MPO (p < 0.05)." (PMID 34177825, 2021). "We found that, for the identification of E. coli infection and other infection groups, the addition of IL2 did not increase the AUC of the other two genes." (PMID 38066783, 2023). "However, E. coli infection before AAD phase suppressed Th2 cytokines IL-4 and serum IgE production, but in contrast enhanced Th1 cytokines IFN-γ and IL-2 production, Moreover, this effects were more significantly in the (108infN+OVA) group than the (106infN+OVA) and (108infA+OVA) group." (PMID 23536867, 2013).
falciparum malaria (5 papers, 2008 to 2020). "To investigate the function of non-Vγ9 γδ T cells after P. falciparum infection, we cultured whole PBMCs from falciparum malaria patients in the presence of IL-2 and crude Pf Ag for 10 days." (PMID 28769886, 2017). "In both P. yoeliiyoelii 17XNL infection and in falciparum malaria, IL-2 is necessary for the expansion of CD25Foxp3 CD4+ T cells (T regulatory cells, or Tregs) and for activating natural killer (NK) cells, which function in the lysis of infected erythrocytes (79, –, 81)." (PMID 32958528, 2020). "Thus, high circulating levels of sCD25 are mostly accompanied by decreased membrane expression of CD25 on T-cells resulting in attenuated proliferation and IL-2 release upon further challenge by additional stimuli in the microenvironment in vivo such as during falciparum malaria." (PMID 30563486, 2018). "The lack of detectable IL-2 in the children with uncomplicated falciparum malaria in this study could be because it is bound to a soluble IL-2 receptor and missed by the assay." (PMID 18312656, 2008).
Giardia infection (5 papers, 2018 to 2022). "First we studied cytokines that earlier have been shown to be up-regulated during Giardia infections in mice, i.e. IL-1, IL-2, IL-4, IL-5, IL-9, IL-10, IL-12, IL-17a, IL-17c, IFN-γ, TGF-β, and TNF-α." (PMID 34335577, 2021). "While several researchers observed a high level of IL-2, IL-4, and IL-10 in the infected group as compared to the control group, there are reports that state the level of IL-4 was decreased in patients with giardiasis." (PMID 36065350, 2022). "Some studies show that individuals with giardiasis have TNF-α and IL-2 high, similar to Th1 response." (PMID 29541642, 2018). "Untreated Giardia-infection may regulate innate and adaptive immune responses mediated by Th17 CD4+T cells and induction of Th1, Th2 and Th17 cytokines, including IL-2, IL-5, IL-6, IL-8, IL-12, IL-13, IL-23, IFN-γ and TNF-α." (PMID 30412580, 2018). "In HF conditions, Giardia infection resulted in increased expression of Tnf-α (3.3-fold; p < 0.05) and Il-6 (4.2-fold; p < 0.05) compared with HF controls (Il-2 and Il-12 mRNA could not be detected in jejunal tissues)." (PMID 34552170, 2021).
gingivitis (5 papers, 2018 to 2025). A disorder involving inflammation of the gums; may affect surrounding and supporting structures of the teeth. "The same study underlined that the sustain of the gingivitis is correlated to a Th1 cell-mediated response and overexpression of IL-2 and IFN-ɣ." (PMID 35735643, 2022).
gout (5 papers, 2018 to 2024). A condition characterized by painful swelling of the joints, which is caused by deposition of urate crystals. "LINC01229 also associates with inflammation- and gout-relevant GO terms including ‘interleukin β secretion,’ ‘T-cell differentiation,’ and ‘interleukin 2 biosynthetic process’." (PMID 30719032, 2018). "In the future, in-depth studies should be conducted to determine whether differences in Th17/Treg imbalance and IL-2 in the different age of onset- gout are caused by T-cell senescence and disruption of immune tolerance with aging." (PMID 38240927, 2024). "Cytokine levels, including IFN-γ, TNF-α, IL-2, IL-4, IL-6, IL-10 and IL-17, were detected in early-onset gout, late-onset gout and HCs." (PMID 38240927, 2024). "The correlation analysis of serum cytokine levels with circulating lymphocyte and CD4+T cell subpopulations in gout patients described that IL-2 levels were positively related to the absolute counts of Treg cells (rs = 0.283, p = 0.022)." (PMID 38240927, 2024). "The contents of interleukin 2 (IL-2) were significantly higher than the blank group in acute gouty arthritis rats." (PMID 35464862, 2022). "Additionally, gout patients had significantly higher cytokines levels (including IL-2, IL-4, IL-6, IL-10, IL-17, IFN-γ, and TNF-α) than HCs; IL-2 levels were positively correlated with Treg cells and negatively correlated with ESR." (PMID 38240927, 2024). "The elevated IL-2 levels in gout patients were negatively correlated with ESR levels." (PMID 38240927, 2024). "Gout is also recognized as an autoinflammatory disease, and it has been found that elevated levels of the serum cytokine IL-2 may play a key role in the pathogenesis of gout, and restoration of Th17/Treg homeostasis may be a potential therapeutic direction." (PMID 39734218, 2024). "IL2RA is the receptor of IL-2, and IL-2 is the inflammatory markers of gout." (PMID 35464862, 2022). "Furthermore, IL-2 levels positively correlated with Treg cells IL-2 levels, suggesting restoring Treg cells levels may be a potential treatment for gout." (PMID 38240927, 2024). "Similarly, low-dose IL-2 therapy based on stimulating Treg cells proliferation and restore immune tolerance may offer new directions for exploring the treatment of late-onset gout." (PMID 38240927, 2024). "Then, we compared cytokine levels, including IFN-γ, TNF-α, IL-2, IL-4, IL-6, IL-10 and IL-17 among gout with tophus, gout without tophus and HCs." (PMID 38240927, 2024). "The correlation analysis in gout patients showed that there were significantly negative correlations in the levels of IL-2 and ESR (rs = − 0.303, p = 0.014), while IL-10 was positively related to BMI (rs = 0.261, p = 0.035)." (PMID 38240927, 2024).
hemorrhage (5 papers, 2013 to 2021). Loss of blood from the vascular compartment to the exterior or into nonvascular body space as a result of rupture or severance of the blood vessels. "The contents of IL-2, IL-4 and TIPE2 produced by splenic CD4+ T lymphocytes were decreased following trauma-hemorrhage, which were normalized by administrations of E2 or PPT, but not DPN or G1." (PMID 33820957, 2021).
hyperferritinemia (5 papers, 2014 to 2022). "MODS and extreme hyperferritinemia were noted on HD 3, and on HD 4, IL-6 was elevated (81 pg/mL) as was soluble IL-2 receptor (8,043 pg/mL), with a normal value for IL-2." (PMID 35360192, 2022). "On HD 67, both IL-2 and IL-6 were elevated (1,060 and 12,376 pg/mL, respectively; the last dose of tocilizumab was 12 days earlier) and the following day extreme hyperferritinemia (31,085 ng/mL) was noted a fourth time." (PMID 35360192, 2022). "Laboratory tests reveal hyperferritinemia (often >10,000 μg/L), increased serum concentration of soluble receptor α for interleukin-2 (>2,400 U/L), hypertriglyceridemia, hypofibrinogenemia, coagulopathy, hyponatremia, hypoproteinemia, and elevated liver transaminases and bilirubin." (PMID 24509696, 2014). "Indeed, in addition to significantly reducing the serum levels of IL-6 and C-reactive protein (CRP), ruxolitinib could influence the regulation of several inflammatory cytokines (including IL-2, IL-5, and IL-10), and consequently reduce hyperferritinemia." (PMID 33489899, 2020).
immune thrombocytopenia (5 papers, 2013 to 2024). "Conversely, the administration of low-dose IL-2 to adult patients with immune thrombocytopenia (ITP) results in a significant augmentation of T regulatory (Treg) cells and platelets." (PMID 38256942, 2024). "Low dose IL-2 increased regulatory T cells and elevated platelets in a patient with immune thrombocytopenia." (PMID 34130625, 2021). "Both IL-2 and P-selectin mediate CD8+ T cells, and both IL-2 and GPIIb/IIIa are involved in the immune thrombocytopenia related CD8+ T cells." (PMID 29207652, 2017). "It has been documented that patients with immune thrombocytopenia have high rates of mononuclear cell proliferation as well as lymphocytes that secrete greater amounts of IL-2 compared to controls." (PMID 23556539, 2013). "In the peripheral blood of children with immune thrombocytopenia (ITP), the frequency of TFR cells in the peripheral blood decreased, the frequency of TFH cells increased, the level of plasma IL-2 decreased, and the level of plasma IL-21 increased." (PMID 29312316, 2017).
iron deficiency (5 papers, 2011 to 2025). "In contrast, and at variance with our previous finding that expression of cytokine proteins such as IL-8, MCP-1, GRO, GROα, IL-2 and IL-3 was enhanced with magnesium deficiency, the array analysis found little impact of low magnesium on interleukins and their associated signaling pathway." (PMID 36079843, 2022). "In addition, iron deficiency has been reported to cause non-proliferating, altruistic T cells to produce IL-2." (PMID 39296289, 2024).
ischemia (5 papers, 2020 to 2025). A hypoperfusion of the BLOOD through an organ or tissue caused by a PATHOLOGIC CONSTRICTION or obstruction of its BLOOD VESSELS, or an absence of BLOOD CIRCULATION. "In the vehicle/ischemia group, many of microglia were colocalized with IL-2." (PMID 31940961, 2020). "To investigate whether LA reduced pro-inflammatory M1 microglia following TFI, we carried out double immunofluorescence staining for IL-2 as pro-inflammatory cytokine and Iba-1 in the vehicle/ischemia and 50 mg/kg LA/ischemia groups." (PMID 31940961, 2020). "Given that CD8+ differentiation can be affected by IL-2 homeostasis; one group showed that IL-2 monoclonal antibody can preserve white matter integrity following experimental ischemia and therefore may be a useful therapeutic target." (PMID 32477327, 2020). "Nonetheless, repeated systemic intravenous hiPSC-MSC infusion in the MSC-MSC/week and MSC-MSC/3 days groups significantly decreased IL-2 and MCSF compared with the ischemia group (all p < 0.05)." (PMID 36008710, 2022). "Studies have shown that low levels of TNF-α may have a protective effect on the heart by enhancing myocardial tolerance to ischemia, and TNF-α may inhibit the expression of inflammatory cytokines such as IL-1, IL-2, and IL-6 in the heart." (PMID 40284832, 2025). "The IL-2/IL-2 antibody complex (IL-2/IL-2Ab) has been shown to increase the number of Tregs and promote the expression of CD39 and CD73 in expanded Tregs in experimental ischemia models." (PMID 32477327, 2020).
juvenile idiopathic arthritis (5 papers, 2013 to 2023). Juvenile idiopathic arthritis (JIA) is the term used to describe a group of inflammatory articular disorders of unknown cause that begin before the age of 16 and last over 6 weeks. "This is consistent with previous findings, in which PD-1 positively correlated with ALT levels, was highly expressed on IL-2–producing tissue-resident CD8+ T cells, and was associated with non-HBV models of chronic inflammation, such as juvenile idiopathic arthritis or polyomavirus encephalitis." (PMID 36594467, 2023).
Lymphadenopathy (5 papers, 2010 to 2022). Enlargement (swelling) of a lymph node. "Results obtained in mice deficient for IL-2 or its receptor, which develop extensive lymphadenopathy and die of systemic auto-immunity early after birth, extended the role of IL-2 from a “T Cell Growth Factor” to “the gatekeeper of immunological tolerance”." (PMID 23801992, 2013). "Reduced FasL (CD178) expression has been implicated in the lymphadenopathy in Il2−/− mice but FasL expression in Sf.Il2−/− mice was no less than that in Sf mice." (PMID 24832045, 2012).
lymphoproliferative disorders (5 papers, 2006 to 2023). "IL-2 is known for inducing and promoting T cell proliferation, but it also is involved in termination of T cell responses, since mice deficient in IL-2 or IL-2R suffer from a lymphoproliferative syndrome." (PMID 33584708, 2020). "Furthermore, IL-2 has been shown to upregulate CTLA-4 (cytotoxic T-lymphocyte-associated protein 4; CD152), and CTLA-4-deficienciy leads to a fatal lymphoproliferative disease that is more aggressive than the lymphoproliferative disorders caused by either IL-2 or Fas deficiency." (PMID 16759382, 2006). "While the proliferative properties of IL-2 have been recognized since its discovery, the importance of IL-2 in cell death was revealed after the generation of IL-2 knockout mice, which develop a lymphoproliferative disorder." (PMID 25019288, 2014). "For instance, several groups have reported that in IL-2 and IL-2R knockout mice, the lymphoproliferative syndrome could be prevented by rIL-2 injection and bone marrow transplantation from wild-type mice." (PMID 21647403, 2011).
metastatic prostate carcinoma (5 papers, 2001 to 2020). A carcinoma that arises from the prostate gland and has spread to other anatomic sites. "Clinical trials and other studies starting in the 1990s have found that high dose IL2, IFN-α, and IFN-Υ induced objective PSA response in metastatic prostate cancer." (PMID 32552802, 2020). "Examples include the addition of a peptide vaccine to the administration of high dose interleukin-2 (IL-2) and the use of a GMCSF-secreting tumor vaccine in combination with CTLA-4 blockade for metastatic prostate cancer." (PMID 27294163, 2016).
mood disorder (5 papers, 2016 to 2024). A cognitive disorder a disturbance in which the person's mood is hypothesized to be the main underlying feature. "In this study, we observed that IL-2 was significantly higher in MDD adolescents than in healthy volunteers, which is in agreement with previous reports in adolescents with mood disorders." (PMID 30662368, 2018).